OLIG2 (oligodendrocyte transcription factor 2)
Diseases named in the same sentence as OLIG2 in open-access papers (continued):
Sharing a sentence is not in itself a finding about the gene and the disease.
glioma (continued). "LGG85 cells grow as neurospheres, express nestin (NES), an intermediate filament specific for neural immature cells, as well as two transcription factors highly expressed in gliomas (OLIG2, SOX2)." (PMID 32218467, 2020). "Olig2 is expressed in multiple grades of human glioma and is required for gliomagenesis in murine models of glioma." (PMID 32483381, 2020). "Hypermethylated regions specific to G34R-mutated gliomas were enriched for CGIs, including those of OLIG1, OLIG2, and canonical histone genes in the HIST1 cluster." (PMID 32999376, 2020). "Recently, the direct roles of NFIA and OLIG2 in tumor development in glioma mouse models were also tested." (PMID 32573857, 2020). "TSM-phosphorylated Olig2 enhances chemoresistance and radioresistance of human gliomas, but the precise mechanisms remain elusive." (PMID 32483381, 2020). "CD133 accompanying with other neural and hematopoietic stem cell marker including Musashi-1, Nestin, Sox2, and Olig2 can identify glioma stem cells from different molecular subtypes of glioma." (PMID 32695001, 2020). "More importantly, Olig2 protein is synergistic with Sox2, Pou3f2 and Sall2 and is a key transcription factor of glioma initiating cells." (PMID 32943100, 2020). "The oligodendrocyte transcription factor 2 (Olig2) was identified as a marker for glioma stem cells." (PMID 32160197, 2020). "Since JQ1-sensitive cells express high levels of both OLIG2 and LGR5, we anticipate that BET inhibition specifically targets the proneural glioma stem cell niche and makes these cells even more susceptible to genotoxic effects of TMZ." (PMID 31754113, 2019). "In additional quantification of anti-proliferatory Dex effects, we analysed the expression of Olig2 known as a transcriptional regulator of proliferation and glioma tumorigenesis." (PMID 30443853, 2019). "The current diagnosis of canine glioma is based on morphologic criteria and immunohistochemistry (IHC), including oligodendrocyte transcription factor 2 (Olig2), glial fibrillary acidic protein (GFAP), and 2′, 3′ cyclic nucleotide phosphatase (CNPase)." (PMID 31803765, 2019). "Results from three independent experiments are shown for Sox2 and Olig2 V5 tagging using mouse neural stem (NS) and glioma-initiating neural stem (GNS) cells." (PMID 29638216, 2018). "OLIG2 is required for proliferation of multipotent neural progenitors and for glioma formation in a mouse model of gliomagenesis and it is also expressed in replicating oligodendrocyte precursor cells where it cooperates with ASCL1 to specify oligodendrocytes." (PMID 29759978, 2018). "While the phosphorylated form of OLIG2 is essential for glioma cell proliferation, we discovered that unphosphorylated OLIG2 promotes glioma invasion through upregulation of the TGF-β2 signaling pathway." (PMID 28821904, 2018). "The immunohistochemical expression of glial cell markers, such as glial fibrillary acidic protein or oligodendrocyte transcription factor (OLIG2), suggests a glial tumor." (PMID 29881714, 2018). "Fluorescent immunostainings of brain sections from tumor-bearing mice showed that tumors express the oligodendrocyte lineage and glioma markers Olig2 and NG2." (PMID 30131568, 2018). "Olig2, a transcription factor that is highly expressed by gliomas, was observed within cells residing in both the tumor core and the invasive rim region." (PMID 28358926, 2017).
glioma (continued). "Consistently, SIRT1 expression was clearly increased in F3.EGFRviii spheres, along with OLIG2, which has recently been characterized in glioma and GSCs." (PMID 28830458, 2017). "IMP3 silencing also resulted in the downregulation of four glioma reprogramming transcription factors- OLIG2, POU3F2, SOX2 and SALL2 in GSCs." (PMID 28465487, 2017). "Twenty-two compounds of the 95 tested exhibited considerable potency against GBM cells in vitro, and were screened initially using tumorigenic Ink4a/arf EGFR-VIII mouse glioma stem cells because these cells express high levels of OLIG2." (PMID 26517684, 2017). "Tumors expressed the astrocyte marker Gfap, oligodendrocyte lineage and glioma marker Olig2, proliferative marker Ki67, and phosphorylated extracellular kinase (phospho-Erk), indicative of active MAPK pathway signaling." (PMID 27713119, 2016). "All malignant gliomas express OLIG2, and inhibiting the OLIG2 pathway inhibits glioma growth and sensitizes to radiation." (PMID 27447975, 2016). "In both in vitro and in vivo studies, it was found that endothelial cells, when cocultured with glioma cells, promoted the phenotype of CSC-like glioma cells, increasing the expression genes such as Sox2, Olig2, Bmi1, and CD133 and their tumorigenicity." (PMID 26880981, 2016). "As expected, the target genes have a lower expression than OLIG2 in the lower grade glioma cases, whereas a higher expression than OLIG2 in the GBM cases." (PMID 27160082, 2016). "Using The Cancer Genome Atlas (TCGA) data, we inferred the homeobox-regulated genes’ expression is higher in 548 GBM cases than in 27 lower grade glioma cases giving that OLIG2 expression can be a reference." (PMID 27160082, 2016). "OLIG2, a basic helix-loop-helix (bHLH) transcription factor, is selectively expressed in a subgroup of glioma cells and required for glioma formation in a murine GBM model." (PMID 25365423, 2014). "As Olig2 expression marks all tumor cells of our glioma model, this effectively labels tumor cells with GFP." (PMID 25330836, 2014). "OLIG2, a proliferation regulator and glioma progenitor cell marker upregulated in IGCs was found to function in enhancing migration and stemness of GSCs." (PMID 25365423, 2014). "Inhibition of OLIG2 expression reduced migration and stemness and provided functional confirmation as a potential therapeutic target in glioma invasion." (PMID 25365423, 2014). "Olig2 has been shown to be expressed in neural progenitor cells and glioma CSCs, which are proposed to be self-renewing cells that promote tumor initiation and heterogeneity." (PMID 23451236, 2013). "Ribosome-bound and total cellular RNA samples from Olig2+mouse glioma cells were quantified by expression microarray." (PMID 23056544, 2012). "To determine if loss of PTEN altered the homeostatic translation state in glioma, we delivered RCAS-Cre virus along with RCAS-PDGFB into Ntv-a/Ink4a/Arf−/−/PTENfl/fl mice and collected ribosome-bound and total cellular RNA from Olig2+cells." (PMID 23056544, 2012). "The tumor bulk in the PDGF-driven model of glioma expresses Olig2, while the GFAP-expressing cells are part of the tumor stroma." (PMID 22393407, 2012). "PDGF-induced gliomas were generated in mice transgenic for the gene fusion of the large ribosome subunit protein L10a with eGFP under the transcriptional control of an Olig2 BAC promoter." (PMID 23056544, 2012). "The ability to distinguish tumor cells from tumor stroma by Olig2 expression allowed us to develop a method for global quantification of translation efficiency for individual mRNAs in glioma cells residing in their native tumor microenvironment." (PMID 23056544, 2012). "The HMG-box transcription factor Sox2 and the bHLH protein Olig2 constitute additional examples of factors commonly expressed by glioma cells and stem cells of the embryonic and adult brain." (PMID 21483788, 2011).
glioma (continued). "Olig2, which is present in oligodendrocyte progenitors, and serves as a marker for human gliomas, was increasingly expressed in areas with accumulation of cells in the PDGF-AL brains." (PMID 21490965, 2011). "On the contrary, PDGF-B-induced gliomas expressed high levels of oligodendrocyte progenitor markers such as the transcription factor Olig2 and the receptor PDGFR-alpha." (PMID 20939912, 2010). "In this case CRX and the germ cell transcription factor OCT4 were negative and showed no intranuclear reactivity in tumor cells, while OLIG2 exhibited strong nuclear staining consistent with a high-grade glioma arising principally in the pineal region." (PMID 19936203, 2009). "More recent work, however, has demonstrated that OLIG1 and OLIG2 are expressed in all glioma subtypes including astrocytoma, ODG, and OAC." (PMID 16018821, 2005). "Our findings reveal OLIG2+ glioma stem-like cells as critical mediators of immune evasion and identify the OLIG2/HDAC7/CXCL10 axis as a potential therapeutic target to enhance immune checkpoint inhibitor efficacy and improve immunotherapy outcomes in aggressive GBMs." (PMID 41591814, 2026). "Oligodendrocyte lineage transcription factor 2 (OLIG2) is a pro-mitotic transcription factor highly expressed in glioma stem cells and may represent a novel therapeutic target." (PMID 41683962, 2026). "While Olig2 is commonly associated with gliomas, including astrocytic tumors, it is not specific to oligodendrogliomas, contrary to common misconceptions." (PMID 40034891, 2025). "For example, OLIG2 was upregulated in IDH-mutant gliomas at the mRNA and protein level." (PMID 38971800, 2024). "Moreover, in the classical GBM subtype, a correlation was confirmed between the CREB5 gene and genes important for stemness of glioma stem cells, such as OLIG2 and NES." (PMID 38418476, 2024). "Importantly, the earliest detectable glioma cells in those models expressed the same molecular markers (Ascl1/Olig2) that we detected in AD-tdTomato+-NSCLs." (PMID 36841240, 2023). "Moreover, it seems gliomas that result from aberrations in OPCs or from regions of highly proliferative cells also tend to show an increase in Olig2 expression." (PMID 37274223, 2023). "Olig2 overexpression drives glioma proliferation and resistance to radiation and chemotherapy." (PMID 37274223, 2023). "Other gliomas, such as astrocytomas and GBMs, have varying Olig2 expression." (PMID 37274223, 2023). "As the result, Olig2 was significantly correlation with stemness in glioma." (PMID 36990974, 2023). "Given the fact that Olig2 influences Wnt signaling in gliomas and neural stem cells and participates in the interaction between Wnt signaling and Notch signaling, further research on the Notch-Olig2-Wnt pathway is important in the area of astrogliogenesis and chronic pain." (PMID 36376699, 2023). "Furthermore, Olig2 plays multiple functions in glioma cell migration, invasion, gliomagenesis, chemotherapy, and radiotherapy resistance." (PMID 36990974, 2023). "Large datasets have confirmed the expression of Olig2 across all gliomas such as TCGA and others." (PMID 37274223, 2023). "Gene network analysis has identified potential roles of Olig2 involvement in gliomas." (PMID 37274223, 2023). "Olig2 dysregulation in gliomas suggests that it is required for glioma growth and formation." (PMID 37274223, 2023). "However, because Olig2 levels vary between different types of gliomas, thorough characterization of genetic targets of distinct glioma types are necessary for the identification of biomarkers and drug development." (PMID 37274223, 2023). "DNTs and DIPGs are examples of such gliomas with marked Olig2 expression." (PMID 37274223, 2023).
glioma (continued). "Importantly, a subtype of Olig2+ oligodendrocyte-like glioma cells was shown to upregulate Wnt7 expression and promote invasion of cancer cells via co-option of existing brain vessels, linking Wnt7 signaling to VCO." (PMID 36119528, 2022). "Furthermore, Wnt7, which is critical for VCO in Olig2+ glioma cells, showed an increased expression in glioma preclinical models and patients after anti-VEGF treatment." (PMID 36119528, 2022). "Olig2 is overexpressed in various malignant cell lines such as lung carcinoma, glioma and melanoma." (PMID 33833342, 2021). "Olig2-positive staining is a marker of glioma of oligodendroglial origin." (PMID 34884748, 2021). "So, OLIG2 driven gliomas might have a relatively better prognosis, which is also demonstrated in this study." (PMID 34565408, 2021). "Furthermore, immunohistochemical analysis of the tumors revealed prominent staining for the human glioma markers Olig2 and Gfap." (PMID 33435218, 2021). "In addition, the oligodendrocyte TF 2 (Olig2) has been reported to be critical in promoting proliferation, migration/invasion, and resistance to radio-/chemotherapy of glioma cells." (PMID 32483381, 2020). "In addition, TSM-phosphorylated Olig2 promotes tumor growth in a genetically defined murine glioma model." (PMID 32483381, 2020). "In the present study, we conducted a single center retrospective analysis evaluating the prognostic role of Olig2 as well as other glioma stem cell and oligodendroglial markers in a glioblastoma cohort using a multivariate analysis including established clinical and molecular prognostic markers." (PMID 32160197, 2020). "Taken together, our results demonstrate that SUMOylation constitutes a pivotal step of Olig2 PTMs for establishing the TMZ resistance in GBM and disrupting Olig2 SUMOylation may have survival benefit in glioma therapy." (PMID 32483381, 2020). "We conclude that GC-GBM is a distinctive subtype of glioma characterized by its vulnerability to DNA damage and that wild-type TERTp and lower OLIG2 function might induce this feature." (PMID 31655917, 2020). "GFAP and Olig2 immunopositivity suggested a glioma, but nothing more precise than that." (PMID 32002518, 2020). "Although phosphorylation of oligodendrocyte transcription factor 2 (Olig2) may contribute to the notorious resistance of gliomas to radiation and genotoxic drugs, the precise mechanisms remain elusive." (PMID 32483381, 2020). "The expression of OLIG2 enables oligodendroglioma anddistinguishes glioblastoma from other astrocytic glial tumors.OLIG2 markers of diffuse glioma are expressed in astrocytomapreclude glioma." (PMID 31312081, 2019). "Knockdownof OLIG2 significantly reduced tumorigenicity in a murine modelof malignant glioma and restored tumorigenic phenotypes showingOLIG2 function was specifically required for glioma formation.OLIG2 bound and repressed the expression of p21 in the inhibitorof the cell cycle 8-14." (PMID 31312081, 2019).
glioma (continued). "In addition to the roles of OLIG2 in glioma stem cell growth, tumour progression and differentiation, a role in tumour initiation, e.g. by promoting cell fate reprogramming of more differentiated cell types into stem-like cancer cells, is possible." (PMID 29759978, 2018). "Furthermore, Olig2 serves as a marker for progenitor cells and glioma stem cells (GSCs) and is required for glioma formation in a genetically relevant murine model." (PMID 29158570, 2017). "In general terms, it seems that, in glioma cells, stemness and mesenchymal phenotype are closely linked: knockdown of genes directly involved in EMT, such ZEB1, also causes inhibition of stem cell regulators like Sox2 and Olig2." (PMID 29261132, 2017). "Moreover, a direct interaction between Olig2 and ZEB1 seems to exist and cause reciprocal stimulation, reinforcing the invasion capacity of glioma cells." (PMID 29261132, 2017). "We noticed that some gB positive cells (green color) exhibit CD11B-negative/CD45-negative phenotype (green color), and the majority of gB positive cells represent a OLIG2-positive subclass of glioma cells (yellow signal of colocalization) or exhibit strong expression for SOX2." (PMID 27517625, 2017). "Furthermore glial tumor markers such as OLIG2 and GLI1 and GSC markers such as MSI1 and SOX2 were also significantly reduced in F3.EGFRviii spheres." (PMID 28830458, 2017). "Oligodendrocyte lineage transcription factor 2 (OLIG2) plays a pivotal role in glioma development." (PMID 27447975, 2016). "On the other hand, the identification of molecules selectively expressed by invasive glioma cells such as OLIG2 may allow the development of therapeutic strategies that specifically target this population of cells." (PMID 25365423, 2014). "Importantly, OLIG2, a proliferation regulator and glioma progenitor cell marker was upregulated in the IGCs relative to the tumor core." (PMID 25365423, 2014). "Intriguingly, OLIG2 is one of most highly expressed genes in the K27M glioma subtype." (PMID 24867641, 2014). "Additionally, RelB regulates expression of Olig2, a regulator of cancer stem cell proliferation and a candidate marker for the cell of origin in glioma." (PMID 23451236, 2013). "In an injury model, these astrocytes are capable of inducing proliferation of Olig2-expressing cells and it is possible that this pro-proliferative astrocyte function may be directed to Olig2-expressing tumor cells in proneural gliomas." (PMID 22393407, 2012). "Hierarchical clustering of PDGF-driven mouse glioma gene expression profiles with various mouse neural cell types characterized these tumor cells as most similar to oligodendrocyte progenitor cells (OPCs) in the normal brain that also express Olig2." (PMID 23056544, 2012). "Similarly to wild type PDGF-B-induced tumors, NG2-KO gliomas harbored an abundant population of recruited OPCs, as revealed by the expression of Olig2 and PDGFR-alpha by the GFP-negative cells in the tumor infiltrated brain regions." (PMID 20939912, 2010). "This confirmed that gliomas with 1p19q codeletion overexpressed neuronal/normal brain genes (AKR1C3, C20orf42, CTTNBP2, L1CAM, GALNT13) as well as genes implicated in gliogenesis and neurogenesis (OLIG2, BMP2, NOG, DCX, ATOH8)." (PMID 18492260, 2008). "Therefore, the expression of survival-associated genes in ODG and OAC can be divided into at least two subgroups; genes such as Olig1 and Olig2 that are expressed in all glial tumors, and genes such as Fabp7 that are restricted to astrocytes." (PMID 16018821, 2005). "Furthermore, Olig2 exerts broad and critical functions across glioma subtypes." (PMID 40428395, 2025).